ERBB2 (erb-b2 receptor tyrosine kinase 2)
Diseases named in the same sentence as ERBB2 in open-access papers (continued):
Sharing a sentence is not in itself a finding about the gene and the disease.
endometriosis (12 papers, 2011 to 2025). The growth of functional endometrial tissue in anatomic sites outside the uterine body. "Among the RTKs associated with endometriosis, Axl and ErbB2 were preferentially activated by PCB126, suggesting their involvement in PCB126-mediated disease progression." (PMID 40951281, 2025). "However, targeting Erbb2 can reverse all apparent female reproductive defects caused by Mig-6 loss including endometrial hyperplasia, infertility, and endometriosis lesion development." (PMID 35232969, 2022). "As MIG-6 decreases with endometriosis progression, ERBB2 increases, which supports the relevance of this pathway to uterine dysfunction in primates." (PMID 35232969, 2022). "To investigate the effect of ERBB2 targeting on endometrial progesterone resistance, fertility, and endometriosis, we introduce Erbb2 ablation in Mig-6d/d mice (Mig-6d/dErbb2d/d mice)." (PMID 35232969, 2022). "We observed increased ERBB2 in the eutopic endometrium from the same baboons over time and with endometriosis progression." (PMID 35232969, 2022). "We next examined the effect of Erbb2 ablation in the endometriosis development of Mig-6d/d mice and found the number and weight of endometriotic lesions were restored to control amounts by the additional ablation of Erbb2." (PMID 35232969, 2022). "In order to investigate the effect of ERBB2 targeting on nonreceptive endometrium and endometriosis with Mig-6 deficiency, we introduced Erbb2 ablation in Mig-6d/d mice (Mig-6d/dErbb2d/d)." (PMID 35232969, 2022). "Here the authors show that progesterone-induced MIG-6 is reduced in endometrium of infertile women and non-human primates with endometriosis, and in a mouse model find that Erbb2 is the key mediator of Mig-6 loss induced endometriosis-related infertility." (PMID 35232969, 2022). "Deeper inquiry into endometrial epithelial-stromal crosstalk between ErbB2/ERK/ESR1 and PGR/MIG-6 signaling pathways will be of major importance to understanding infertility and endometriosis." (PMID 35232969, 2022). "The significant decrease in EGFR, ErbB2, FR-alpha, and HE4 in the PF of endometriosis patients compared to controls should be further evaluated." (PMID 32604857, 2020). "Together, our results demonstrate that ERBB2 overexpression in endometrium with MIG-6 deficiency causes endometrial progesterone resistance and a nonreceptive endometrium in endometriosis-related infertility, and ERBB2 targeting reverses these effects." (PMID 35232969, 2022). "However, our data from a baboon endometriosis model shows a significant inverse correlation between MIG-6 and ERBB2 in the eutopic endometrium." (PMID 35232969, 2022). "In endometriosis, PEA technology identified seven proteins up-regulated (IL-6, IL-8, CCL 19, SCF, VEGF-D, IL-6RA, MIA9) and ten proteins down-regulated (ICOSLG, EGFR, SELE, ErbB2/HER2, IL-6RA, VEGFR-2, Flt3L, CXCL10, HE4, FR-alpha)." (PMID 36009404, 2022). "The results of an immunohistochemical study analyzing the expression of ErbB2 in endometriotic tissue suggested no significant involvement of this receptor in the pathogenesis of endometriosis." (PMID 32604857, 2020). "As our results showed a significant decrease in ErbB2 in the PF of endometriosis patients, this supports the theory that ErbB2 does not play a role in the pathogenesis of this disease." (PMID 32604857, 2020). "We then examined the expression of ERBB2 in the induced endometriosis of nonhuman primates." (PMID 35232969, 2022).
medullary carcinoma (12 papers, 2011 to 2023). "PDL1 expression was generally associated with poor-prognosis features: pathological type (with more ductal and medullary carcinoma in the “PDL1-up” group), large pathological tumor size, high tumor grade, negative ER status, negative PR status, positive ERBB2 status, and positive Ki67 status." (PMID 25669979, 2015).
myocardial infarction (12 papers, 2012 to 2025). Gross necrosis of the myocardium, as a result of interruption of the blood supply to the area, as in coronary thrombosis. "Some studies indicate that the activation of NRG1/ErbB2 can be an effective molecular strategy in the repair and regeneration of cardiac muscle after a heart attack." (PMID 32509881, 2020). "The exercise training is a way to activate NRG1/ErbB2 that has been able to improve the recovery and regeneration of cardiac muscle and reduce fibrosis in rats with heart attack." (PMID 32509881, 2020). "Constitutive overexpression of Erbb2 results in an enlarged heart characterized by extensive cardiomyocyte hypertrophy, dedifferentiation and proliferation, whereas transient induction of ERBB2 promotes cardiomyocyte dedifferentiation and regeneration after myocardial infarction." (PMID 33178704, 2020). "A positive role for Runx1 was also suggested by its upregulation in hearts treated with oncostatin M, which has been shown to protect the heart after acute myocardial infarction, as well as in hearts that overexpress Erbb2 and show enhanced myocardial proliferation and regeneration." (PMID 32341028, 2020). "Analysis of RTK expression in the acute myocardial infarction samples revealed 4 RTKs with significantly reduced expression (EGFR, ERBB2, ERBB3 and EPHA2) when compared to healthy heart." (PMID 30342492, 2018). "When comparing healthy hearts with hearts representing acute myocardial infarction, significant downregulation of EGFR, ERBB2, ERBB3, as well as EPHA2, was discovered in the infarcted heart, ERBB2 demonstrating the greatest difference in expression." (PMID 30342492, 2018).
cervical squamous cell carcinoma (11 papers, 2008 to 2025). A squamous cell carcinoma arising from the cervical epithelium. "ERBB2 mutations concomitantly harbored PIK3CA or KRAS mutations were found in non-squamous cervical cancer." (PMID 32922530, 2020).
clear cell renal cell carcinoma (11 papers, 2018 to 2025). "It indicated that the ERBB2 gene was not a malignant indicator in some cancer types, such as kidney chromophobe, renal clear cell carcinoma, and kidney renal papillary cell carcinoma, which is a mutated hetero-morphism of the kidney tissues." (PMID 36172165, 2022).
schizophrenia (11 papers, 2007 to 2023). A major psychotic disorder characterized by abnormalities in the perception or expression of reality. "A further link with published data on schizophrenia is provided by prostatic acid phosphatase, seen to be increased here, which dephosphorylates Erbb2, a receptor for the schizophrenia susceptibility gene product neuregulin." (PMID 23118852, 2012). "Additionally, heterozygous reeler and ErbB2/B4-CNS knock-out mice models show impaired dendrite spines and behavioral abnormalities that might be affected by perturbation of glutamatergic synapses associated with schizophrenia-like symptoms in various brain regions." (PMID 37670703, 2023). "Of these pathways, schizophrenia appears to have to strongest link to the Nrg/ErbB pathway, and SNPs in several of the genes encoding Nrg (NRG1, NRG2, NRG3, and NRG6) and all of the genes encoding ErbB receptors (EGFR, ERBB2, ERBB3, and ERBB4) have been linked to schizophrenia." (PMID 30618607, 2018). "The expression of ErbB2 and ErbB3 receptors was unaltered in schizophrenia." (PMID 28646138, 2017). "Only four SNPs were studied in ERBB2, and none of these was found to be significantly associated with schizophrenia." (PMID 17598910, 2007). "Notably, IL17a identified alterations in signaling by ERBB2 factors, which is a pathway of particular relevance to schizophrenia given its interaction with neuregulin-1 to mediate cell adhesion, its potential role in schizophrenia risk, as well as antipsychotic response/treatment." (PMID 34158620, 2021). "Six drugs that could treat schizophrenia were found to target ERBB2." (PMID 32398742, 2020). "The crosstalk of PID candidate pathway for schizophrenia between hedgehog signaling pathway and other cancer-related pathways such as LKB1 signaling events, Aurora signaling pathway, ErbB2/ErbB3 signaling pathway and TNF alpha/NFkB signaling pathway." (PMID 25522158, 2014).
small cell carcinoma (11 papers, 2015 to 2025). A neuroendocrine carcinoma composed of small malignant cells which are often said to resemble "oat cells" under the microscope. "Mechanisms of resistance to osimertinib primarily include secondary EGFR mutations (e.g., C797S), MET and erythroblastic oncogene B-2 (ERBB2) amplification, or histological transformation to small cell carcinoma, among others." (PMID 38213544, 2023). "Other mechanisms include small cell carcinoma transformation, gene amplification of EGFR, ERBB2, and MET and additional mutations in PI3K, BRAF, and KRAS32–36." (PMID 33863951, 2021).
thymoma (11 papers, 2017 to 2025). A neoplasm arising from the epithelial cells of the thymus. "In this study, 3 of 19 (16%) thymomas exhibited missense variants of uncertain clinical significance in ERBB2 [p.(Ser703Arg)], KIT [p.(Ile690Val)], and FOXL2 [p.(Pro157Ser)]." (PMID 35884448, 2022). "By the ssGSEA method, we proved that CTNNB1, EGFR, SOX2, and ERBB2 expressions showed significant correlation with Th17 T cell in thymoma, and KEGG analysis suggested that differential genes were highly enriched in the IL-17 pathway." (PMID 39192657, 2025). "Another frequent missense variant was ERBB2 p.(Ile655Val), which was classified in 21 of 53 (40%) TET patients (16 of 34 [47%] thymic carcinomas and 5 of 19 [26%] thymomas) as homozygous or heterozygous." (PMID 35884448, 2022). "The ERBB2 and KIT variants were detected in B2B3 thymomas, and the FOXL2 variant in a micronodular thymoma with lymphoid stroma." (PMID 35884448, 2022). "CTNNB1, EGFR, SOX2, and ERBB2 expressions revealed a significant correlation with NK cells in thymoma, and these four genes may play a role in regulating NK cells in TAMG." (PMID 39192657, 2025). "No pathogenic variants were found in thymomas, although a few variants of uncertain clinical significance were present in KIT, ERBB2, and FOXL2." (PMID 35884448, 2022).
atherosclerosis (10 papers, 2012 to 2026). A disease characterized by the build-up of fatty material and calcium deposition in the arterial wall resulting in partial or complete occlusion of the arterial lumen. "Mouse-specific atherosclerosis mechanisms identified in the aorta include signaling by insulin receptor, EGFR, ERBB2, NGF, and TGF-beta signaling, axon guidance, VEGF and VEGFR pathways, and Tap63 and DeltaNp63 pathways." (PMID 38060277, 2023).
Barrett esophagus (10 papers, 2010 to 2025). Esophageal lesion lined with columnar metaplastic epithelium which is flat or villiform. "To further examine the molecular changes in OAC samples containing high levels of ERBB2 expression (defined as >2SD above the median level), we compared their RNA-seq profiles with those found in Barrett's oesophagus patients." (PMID 36694726, 2023). "Conversely, FOX and GATA factors showed reciprocal behaviour and were more enriched in regions more open in Barrett's oesophagus and which opened following ERBB2 inhibition in OE19 cells." (PMID 36694726, 2023).
neuropathy (10 papers, 2019 to 2025). A disorder affecting the nervous system that manifests with pain, tingling, numbness, and/or muscle weakness. "Furthermore, an impact of DNM2-mediated internalization on surface receptors (potentially also altering signaling) is indirectly supported by studies in cell culture, showing that expression of a neuropathy-associated DNM2 mutant alters surface levels of integrin β1 and ErbB2." (PMID 30648534, 2019).
sarcopenia (10 papers, 2018 to 2026). Progressive decline in muscle mass due to aging which results in decreased functional capacity of muscles. "The 5 genes (AXL, GAB1, ERBB2, NRP2, and ESR1) along with 13 pharmacological agents represent promising candidates for enhancing the treatment of osteoporosis and sarcopenia." (PMID 40660573, 2025). "The identification of ESR1, NRP2, AXL, ERBB2, and GAB1 as key genes provides novel therapeutic targets and highlights the importance of understanding shared molecular pathways in osteoporosis and sarcopenia." (PMID 40660573, 2025).
acute respiratory distress syndrome (9 papers, 2019 to 2025). Progressive and life-threatening pulmonary distress in the absence of an underlying pulmonary condition, usually following major trauma or surgery. "In one published incident, fatal adult respiratory distress syndrome occurred rapidly following infusion of > 1010 T-cells, targeted against ErbB2 using a trastuzumab scFv coupled to a fused CD28/4-1BB/CD3ζ endoplasmic domain." (PMID 31910217, 2020). "Data from animal and human models of non-infectious acute lung injury and acute respiratory distress syndrome indicate that ErbB1 and ErbB2 are key regulators of inflammation and tissue injury via activation of the p38 MAPK, AKT/mTOR, and Ras/RAF/MEK/ERK pathways." (PMID 37581931, 2023).
papillary adenocarcinoma (9 papers, 2008 to 2025). A morphologic variant of adenocarcinoma.
testicular cancer (9 papers, 2013 to 2025). A primary or metastatic malignant neoplasm that affects the testis. "We recently showed that testicular cancer cells are very sensitive to dual anti-ErbB1 and anti-ErbB2 inhibitors such as lapatinib, in contrast with the very weak effect obtained with pure anti-ErbB1 inhibitors." (PMID 23937707, 2013).
uterine carcinosarcoma (9 papers, 2021 to 2025). A usually aggressive malignant neoplasm arising from the uterine corpus and less often the cervix. "A more recent clinical study using an optimized HER2-targeted antibody-drug conjugate (trastuzumab deruxtecan) in patients with HER2 (encoded by ERBB2) immunohistochemistry high (2+ or 3+) and low (1+) uterine carcinosarcoma found clinical efficacy in both HER2-high and -low groups." (PMID 41202566, 2025).
autoimmune disease (8 papers, 2020 to 2025). A disorder resulting from loss of function or tissue destruction of an organ or multiple organs, arising from humoral or cellular immune responses of the individual to their own tissue constituents. "The inflammasome activation and the IL-7 and ErbB2-ErbB3 pathways conferred susceptibility to other autoimmune diseases like SLE and psoriasis or T1D including in another Brazilian cohort." (PMID 35058920, 2021).
chondrosarcoma (8 papers, 2012 to 2024). A malignant cartilaginous matrix-producing mesenchymal neoplasm arising from the bone and soft tissue. "While in the rat chondrosarcoma cell line, Erbb2 promoter unmethylation seems to be the main cause for Erbb2 overexpression, our data suggests a different pivotal epigenetic mechanism underlying the expression of this gene." (PMID 22253826, 2012). "Simultaneously, a reduction in miR-125b levels promotes the proliferation of chondrosarcoma cells, exerting this effect through its targeted regulation of ErbB2." (PMID 38542153, 2024). "The inhibitory function of miR-125b in ErbB2 not only impacts glucose metabolism but also increases the sensitivity of chondrosarcoma cells to the chemotherapeutic drug doxorubicin." (PMID 38542153, 2024). "BCAR4 was also reported to promote chondrosarcoma cell proliferation through activation of mTOR19, a downstream target of ERBB2/ERBB3 signalling." (PMID 32193429, 2020). "A similar study to ours was performed in a rat chondrosarcoma cell line, in which an increase in Erbb2 expression was found after global genome demethylation." (PMID 22253826, 2012).
Li-Fraumeni syndrome (8 papers, 2012 to 2022).
mucinous ovarian tumors (8 papers, 2009 to 2023). "Intratumoral heterogeneity among mucinous ovarian tumors, which previously seemed to be restricted to heterogeneity in ERBB2 status (observable in situ using FISH, CISH or IHC), presents a challenge for standard molecular analyses." (PMID 25986173, 2015).
Autoimmunity (7 papers, 2010 to 2024). The occurrence of an immune reaction against the organism's own cells or tissues. "For example, ErbB2-specific CAR+ T cells have been used to control tumours in ErbB2 transgenic mice without autoimmunity, even when administered following preparative lymphodepletion." (PMID 23304553, 2012).
Immunodeficiency (7 papers, 2014 to 2026). Failure of the immune system to protect the body adequately from infection, due to the absence or insufficiency of some component process or substance. "Most of the 313 new disease links belonged to the DisGeNET class neoplasms (n = 40; EGFR, ERBB2, KITLG, AREG) but also to immune diseases (n = 29; FAS), neurological diseases (n = 13; PNPLA6), and cardiovascular diseases (n = 13; CD163)." (PMID 40593564, 2025).
intestinal tumors (7 papers, 2013 to 2024). "For example, an ERBB2-amplified intestinal tumor-like organoid exhibited significant responsiveness to the dual ERBB2/EGFR inhibitor lapatinib, but not to a strain with an epidermal growth factor receptor-amplified status with a normal ERBB2 allele." (PMID 38496762, 2024). "Moreover, we also found that co‐overexpression of the PGAP3 and ERBB2 was correlated with T stage, TNM stage, tumour size and intestinal tumour phenotype in GC." (PMID 37386793, 2023).
soft tissue sarcoma (7 papers, 2017 to 2025). A malignant neoplasm arising from muscle tissue, adipose tissue, blood vessels, fibrous tissue, or other supportive tissues excluding the bones. "Therefore, ErbB2 is also expressed on other than bone sarcomas and Ewing’s family tumors, such as soft tissue sarcomas, including high-risk, relapsed and refractory RMS with alveolar histopathological characteristics, albeit at low levels, making this tumor target clinically relevant." (PMID 29029499, 2017). "As surface expression of ERBB2 is detectable in a substantial subset of alveolar RMS and other tumor entities, the use of CAR T cells targeting ERBB2 was developed in the context of ACT for soft tissue sarcoma (STS)." (PMID 33193388, 2020).